KLHL29 (kelch like family member 29)
Synonyms: KBTBD9; KIAA1921
Tractability: Small molecule: it belongs to a druggable protein family.
Gene: Protein-coding gene on chromosome 2 (23,385,179 to 23,708,611, forward strand). Ensembl gene ENSG00000119771.
Subcellular location (Human Protein Atlas): Mitochondria; Cytosol
Gene Ontology:
Molecular function: protein binding; ubiquitin-like ligase-substrate adaptor activity
Biological process: proteasome-mediated ubiquitin-dependent protein catabolic process
Cellular component: Cul3-RING ubiquitin ligase complex; cytoplasm
Genetic constraint (gnomAD): Loss-of-function variants: 21 observed, 76.04 expected, observed/expected ratio (o/e) 0.28, 90% interval 0.19 to 0.4. The upper end of that interval is the gene's LOEUF score, 0.4, which puts it in group 1 of 6, group 1 being the genes least tolerant of losing a copy. Missense variants: 867 observed, 1,185.8 expected, observed/expected ratio (o/e) 0.73, 90% interval 0.69 to 0.77. Synonymous variants: 511 observed, 511.91 expected, observed/expected ratio (o/e) 1, 90% interval 0.93 to 1.07.
Homologues: Orthologues: chimpanzee KLHL29 (99% identical), macaque KLHL29 (99% identical), rat Klhl29 (98% identical), rabbit KLHL29 (98% identical), dog KLHL29 (97% identical), guinea pig KLHL29 (97% identical), mouse Klhl29 (97% identical), pig KLHL29 (95% identical), tropical clawed frog klhl29 (79% identical), zebrafish KLHL29 (71% identical), zebrafish klhl29 (70% identical). Paralogues in human: KLHL24 (23% identical), KLHL3 (21% identical), KLHL21 (21% identical), KLHL20 (21% identical), KLHL17 (20% identical), KLHL1 (20% identical), KLHL5 (20% identical), KLHL18 (19% identical), KLHL2 (19% identical), KLHL28 (19% identical), KLHL12 (19% identical), KLHL23 (19% identical), and 42 more.
Diseases named in the same sentence as KLHL29 in open-access papers:
KLHL29 is named in the same sentence as 14 diseases in open-access papers, as found by Europe PMC text mining. Sharing a sentence is not in itself a finding about the gene and the disease. The quoted sentences say what the papers report.
Obesity (2 papers, 2012 to 2022). Accumulation of substantial excess body fat. "Furthermore, KLHL29 had good AUCs and a close relation to CD8 T cells, CD4 naive T cells, gamma delta (γδ) T cells, and M2 macrophages in our study, which indicated that KLHL29 had a potential association with obesity and DCM, especially immunologically." (PMID 36547458, 2022). "NOX4, CCDC80, COL1A2, HTRA1, and KLHL29 were identified as key genes by LASSO regression analysis, among which HTRA1 and KLHL29 showed a close association with immune system infiltration in DCM and obesity." (PMID 36547458, 2022). "The key genes, NOX4, CCDC80, COL1A2, HTRA1, and KLHL29 were significantly expressed in DCM, with KLHL29 and HTRA1 especially closely associated with the immune response, which might be markers for obesity-induced DCM and be potential avenues for exploration in immunotherapy." (PMID 36547458, 2022). "The key genes KLHL29 and HTRA1 may play critical roles in obesity-related DCM." (PMID 36547458, 2022).
Bardet-Biedl syndrome (1 paper, 2025). A ciliopathy with multisystem involvement. "Notably, the KLHL29 gene, which is associated with Bardet–Biedl syndrome in humans, and Pcdh15, which is associated with Usher syndrome, were amongthe top 10 DEGs." (PMID 40589789, 2025).
breast carcinoma (1 paper, 2023). "Kaplan–Meier survival analysis indicated that low expression of KLHL29 was associated with poor overall survival and relapse-free survival in basal-like breast cancer from the Kaplan–Meier plotter database." (PMID 37845393, 2023). "KLHL29 expression was significantly downregulated in breast cancer tissues compared with adjacent normal tissues, and low levels of KLHL29 were associated with unfavorable prognoses." (PMID 37845393, 2023).
chronic kidney disease (1 paper, 2012). Impairment of the renal function secondary to chronic kidney damage persisting for three or more months. "When exclusively African-ancestry studies were considered, we found that only 3 connections, between the blood pressure, lipids and chronic kidney disease phenotypes, were reproduced by one genomic region (APOB/KLHL29)." (PMID 23029515, 2012).
coronary heart disease (1 paper, 2015). "The function of KLHL29 is not yet known, but this gene has been implicated in coronary heart disease." (PMID 26121138, 2015).
leiomyosarcoma (1 paper, 2024). An uncommon, aggressive malignant smooth muscle neoplasm, usually occurring in post-menopausal women. "Moreover, a comparative analysis of FGF12 and KLHL29 expression across different sarcoma subtypes and leiomyosarcomas (LMS) revealed a significant difference in KLHL29 expression between HG-ESS and LG-ESS and LMS." (PMID 39676856, 2024).
osteoarthritis (1 paper, 2022). A noninflammatory degenerative joint disease occurring chiefly in older persons, characterized by degeneration of the articular cartilage, hypertrophy of bone at the margins and changes in the synovial membrane. "KLHL29 is a protein-coding gene belonging to the conserved Kelch-like (KLHL) gene family whose expression is associated with micro-fragmented adipose tissue (MF), exerting an anti-inflammatory effect in osteoarthritis." (PMID 36547458, 2022).
sarcoma (1 paper, 2024). A usually aggressive malignant neoplasm of the soft tissue or bone. "While FGF12 may reflect the aggressiveness of the tumor microenvironment, KLHL29’s varying expression levels among different sarcoma types highlight its potential as a biomarker for distinguishing tumor subtypes." (PMID 39676856, 2024). "Our analysis revealed that KLHL29 expression levels vary across different sarcoma subtypes, which may help distinguish between high-grade and low-grade ESS and LMS." (PMID 39676856, 2024).
tumor (3 papers, 2022 to 2024). "To address the molecular mechanism underlying the tumor suppressive functions of KLHL29 in TNBC, we conducted immunoprecipitation (IP) assays coupled with mass spectrometry (MS) analysis of potential KLHL29-interacting proteins in BT549 and CAL51 cell lines." (PMID 37845393, 2023). "Therefore, our study for the first time demonstrates the tumor suppressive role and the underlying mechanism for KLHL29 in TNBC." (PMID 37845393, 2023). "Here, we identified one of the KLHL family members, KLHL29, as a novel tumor suppressor gene in TNBC." (PMID 37845393, 2023). "Collectively, our study uncovers a tumor suppressive role for KLHL29 in TNBC and provides a promising combination strategy for overcoming TNBC chemoresistance." (PMID 37845393, 2023). "In this study, we identified KLHL29, which is an understudied member of the Kelch-like gene family, as a crucial tumor suppressor that regulates chemosensitivity in TNBC." (PMID 37845393, 2023). "In conclusion, our study uncovers KLHL29 as a tumor suppressor in TNBC." (PMID 37845393, 2023). "Furthermore, the tumor suppressive role of KLHL29 was validated using a xenograft tumor model, as depleting KLHL29 significantly increased the size, growth rate, and weight of xenograft tumors." (PMID 37845393, 2023). "Acting as an adapter that bridges the E3-ligase CUL3 and the substrate DDX3X, KLHL29 executes the tumor suppressive function by enhancing the proteasomal degradation of DDX3X, consequently leading to the downregulation of cyclins and cell cycle arrest at G0/G1 phase." (PMID 37845393, 2023). "As expected, knockdown of DDX3X impaired TNBC cell proliferation, migration, and invasion, suggesting that DDX3X is an oncoprotein and KLHL29 might exert its tumor suppressive functions by inhibiting DDX3X, which is further investigated below." (PMID 37845393, 2023). "In this study, we sought to identify tumor suppressors based on the multi-omics data from our TNBC cohort, resulting in the identification of KLHL29, which is an understudied member of the Kelch-like gene family." (PMID 37845393, 2023). "The overexpression of KLHL29 dramatically reduced the growth of MDA-MB-231 cell-derived xenograft tumors, as measured by the tumor size, growth rate, and weight." (PMID 37845393, 2023). "This differential expression suggests that KLHL29 could be valuable for clinical stratification of ESS patients, providing insights into tumor behavior and treatment responses." (PMID 39676856, 2024).
cancer (2 papers, 2018 to 2023). A tumor composed of atypical neoplastic, often pleomorphic cells that invade other tissues. "Remarkably, the DDX3X inhibitor RK33 combined with platinum-based chemotherapy can synergistically suppress TNBC that usually expresses low levels of KLHL29 and high levels of DDX3X using cancer cell-derived xenograft and patient-derived organoids models." (PMID 37845393, 2023). "Eight of these had decreased expression in cancer (KLHL3, KLHL4, KLHL13, KLHL14, KLHL29, KLHL30, KLHL32, and KLHL33) while four genes (ENC1, KLHL12, KLHL17, and KLHL35) had patterns of up-regulated gene expression." (PMID 30647843, 2018). "Only KLHL29, KLHL38, and KLHL22 had hazard ratios or inverse hazard ratios >2 in the same direction with three cancer types." (PMID 30647843, 2018). "KLHLs with significant hazard ratios or inverse hazard ratios for four cancer types regardless of direction were KLHL14, KLHL22, KLHL29, KLHL32, and KLHL36." (PMID 30647843, 2018).
neurodevelopmental disorder (2 papers, 2022 to 2023). A behavioral and cognitive disorder with onset during the developmental period that involves impaired or aberrant development of intellectual, motor, or social functions. "Since there was no experimental evidence for KLHL29 leading to neurodevelopmental disorder, ZMIZ1 was considered as the most potential disease-causing gene." (PMID 35432459, 2022). "Similarly, KLHL29 has already been discussed to be involved in a neurodevelopmental disorder." (PMID 36449109, 2023).
infection (1 paper, 2023). The state of being infected such as from the introduction of a foreign agent such as serum, vaccine, antigenic substance or organism. "Then, we generated KLHL29-stably overexpressing BT549 and CAL51 cells via lentiviral infection, as these two cell lines express very low levels of endogenous KLHL29." (PMID 37845393, 2023).
KLHL29 also shares sentences with these, for which no sentence is quoted: triple-negative breast carcinoma (1 paper); Usher syndrome (1).